BRAF (B-Raf proto-oncogene, serine/threonine kinase)
Diseases named in the same sentence as BRAF in open-access papers (continued):
Sharing a sentence is not in itself a finding about the gene and the disease.
cancer (continued). "Moreover, we have demonstrated that negative feedback can be overcome by inhibiting BRAF in both its monomeric and dimeric form in combination with MEK inhibition leading to more efficacious and tolerable treatment in preclinical BRAF (V600E) cancer models." (PMID 35978321, 2022). "Similarly, SJF-0628 results in the degradation of BRAF-mutant cancers in a dose-dependent manner within four hours with no ERK phosphorylation for up to 72 h and only 30% recovery of BRAF activity after washout within 24 h, highlighting the extended catalytic activity of BRAF-PROTAC treatment." (PMID 41516092, 2025).
adenocarcinoma (158 papers, 2008 to 2026). A common cancer characterized by the presence of malignant glandular cells. "Almost all samples with BRAF mutation (87.5%), seven out of eight, were adenocarcinomas and 75% were men." (PMID 40591555, 2025). "Patients with BRAF V600E mutations typically present with adenocarcinoma and are more likely to have multiple metastases at the time of diagnosis." (PMID 41480531, 2025). "Subsequent whole-exome sequencing studies suggested a higher prevalence, detecting BRAF mutations in 7–8% of adenocarcinomas, with alterations in the MAPK-ERK pathway present in 76% of these cases." (PMID 40332392, 2025). "BRAF mutations in non-small-cell lung cancer account for around 5% of adenocarcinomas, which include two types of sub-mutations: V600 and non-V600." (PMID 40507907, 2025). "It is estimated that 1–3% of NSCLC cases with adenocarcinoma histology exhibit BRAF mutations, with approximately half having BRAF V600E mutations resulting in a constitutively active BRAF kinase." (PMID 38215251, 2024). "BRAF V600E mutations are found in approximately 3% of adenocarcinomas and are mutually exclusive with other driver genes." (PMID 39139611, 2024). "Somatic mutations in BRAF occur in ~3–8% of adenocarcinoma cases; of these, ~50% are BRAF V600E, which is predictive for vemurafenib and dabrafenib-based therapies." (PMID 36765679, 2023). "Patients with BRAF mutation also had a numerically higher PD-L1 expression than wild type adenocarcinoma patients." (PMID 35980949, 2022). "When differences among histological types were examined, the BRAF V600E mutation was detected at a significantly higher frequency in poorly differentiated adenocarcinomas, compared with other histological types (p < 0.0001)." (PMID 35474548, 2022). "The adenocarcinoma I1 and carcinoid I2 components of the mixed neoplasm shared the same mutations in BRAF (p.Gly466Ala), NF1 (p.Pro1359LeufsTer19 and p.Glu1928Ter), STK11 (p.Gly188AlafsTer99), and AKT2 (p.Leu52Ter) genes." (PMID 34926584, 2021). "NGS identified two different BRAF driver mutations G466E and V600_K601delinsE in two lesions of adenocarcinoma in situ, and a BRAF K601E in a lesion of minimally invasive adenocarcinoma." (PMID 33706781, 2021). "Two mucinous cases had a mutation in the BRAF gene again representing 13.3% of the cohort compared to 4.1% of the TCGA adenocarcinoma NOS cohort." (PMID 32984045, 2020). "BRAF mutations were found in 15.4% of the mucinous MSS cohort compared to 1.5% of the adenocarcinoma NOS MSS cohort (p = 0.07)." (PMID 32984045, 2020). "Histopathologically, our CMPT was diagnosed as a benign lesion; however, some reports suggest it to be a precursor of adenocarcinoma because they had confirmed BRAF, EGFR, and ALK mutations, which occur early in lung adenocarcinogenesis." (PMID 32990811, 2020). "Despite these contradictory findings, almost all NSCLC BRAF-mutated cases feature an adenocarcinoma morphology with a micropapillary growth pattern and strong expression of thyroid transcription factor 1 (TTF-1)." (PMID 33260892, 2020). "The present results agree with earlier findings from other regions and countries, showing low incidence of the BRAF V600E mutation that tends to exist in adenocarcinoma." (PMID 33037234, 2020). "In contrast, oncogene-induced senescence is likely to reduce the frequency of the stepwise progression in KRAS- or BRAF-mutated adenocarcinoma." (PMID 29690599, 2018). "Driver genetic mutations, including EGFR, KRAS, and BRAF, are thought to be associated with the initiation and progression of adenocarcinoma as described in this review." (PMID 29690599, 2018).
adenocarcinoma (continued). "The mutation rate of KRAS was significantly different in different histological types, NRAS and BRAF mutations were only detected in adenocarcinomas." (PMID 30416987, 2018). "H508 is a CRC (caecal) adenocarcinoma cell line harboring a heterozygous G596R BRAF mutation (impaired kinase)." (PMID 28947956, 2017). "For BRAF, we observe a high general mutation frequency in adenocarcinomas (9%), with a 3.7% V600 mutation rate." (PMID 28415793, 2017). "Patients with BRAF mutation were associated with adenocarcinoma than those with non‐BRAF mutation (89.3% vs. 70.6%, P = 0.048)." (PMID 28135039, 2017). "Our previous analyses demonstrated that within the 186 adenocarcinomas tested, BRAF and K-RAS mutations occurred together less frequently than expected by chance (χ2 test, p = 0.009)." (PMID 21473780, 2011). "This is the first study to show that KRAS mutations are frequent (45%) in serrated adenocarcinomas, and that the MAPK activation resulting from either KRAS or BRAF mutations is very common (79%) in serrated adenocarcinomas." (PMID 21457162, 2011). "Forty-two per cent of BRAF-mutated serrated adenocarcinomas showed high-level MSI (MSI-H) (P = 0.075), 100% showed hMLH1 methylation (P = 0.001) and 90.9% showed MGMT methylation (P = 0.019)." (PMID 21457162, 2011). "Fifty-nine adenocarcinomas presented with either BRAF or K-ras mutation, only one of which harboured both." (PMID 20233436, 2010). "Primary BRAF-mutated patients had more elderly (median age: 67 versus 61, p=0.015), males (53.4% vs 26.7%, p=0.056), former/current smokers (36.5% vs 6.7%, p=0.033), non-adenocarcinoma (11.4% vs 0%, P=0.351) patients than the acquired BRAF-mutated cohort." (PMID 40242250, 2025). "The BRAF V600E mutation is common in older patients (>60 years), patients with adenocarcinoma." (PMID 35814395, 2022). "BRAF mutations occur in approximately 2–4% of NSCLC patients with adenocarcinoma." (PMID 35814395, 2022). "The BRAF p.(V600E) mutation can be detected in approximately 3% of NSCLC adenocarcinomas." (PMID 34344387, 2021). "It is also estimated that serrated adenocarcinoma has a less favorable survival than traditional adenocarcinoma, which could be partially because of the interaction between smoking and the enrichment of BRAF mutations and CIMP expression levels." (PMID 34377935, 2021). "In addition, NECs share mutations (i.e. KRAS; SMAD4 in the pancreas, BRAF and K-Ras in the colon) with respective adenocarcinomas." (PMID 33855635, 2021). "Our results showed that BRAF mutations are mostly performed in adenocarcinoma." (PMID 32411601, 2020). "Furthermore, similar frequency of MSI, RAS and BRAF mutations have been reported in MACs and adenocarcinomas with a mucinous component (<50%) challenging current definition." (PMID 30842570, 2019). "Additionally, we detected one infrequent EGFR mutation in a sarcomatoid PDX and one BRAF mutation in an adenocarcinoma model." (PMID 25470237, 2015). "BRAF mutation is more specific to serrated adenocarcinomas than KRAS." (PMID 25945086, 2015). "V600E BRAF mutation, a domain subtype of BRAF mutations, was significantly more common in females and was identified in 8.6% of female patients with adenocarcinoma, which is helpful to identify the enriched patient population for treatment with BRAF inhibitors." (PMID 26187152, 2015). "Additionally, we found that sample 6935 had co-occurring mutations in PI3K (PIK3CA) and RTK-RAS (BRAF) pathways, and the patient suffered a poorly differentiated adenocarcinoma in the ascending colon." (PMID 25617745, 2015). "BRAF mutations were frequent (33.3%; 14/42) and specific to serrated adenocarcinomas." (PMID 21457162, 2011). "Primary BRAF-mutated patients preferentially occurred in the elderly (median age: 67 vs 61, p=0.015), males (53.4% vs 26.7%, p=0.056), former/current smokers (36.5% vs 6.7%, p=0.033), non-adenocarcinoma (11.4% vs 0%, P=0.351) compared to acquired BRAF-mutated patients." (PMID 40242250, 2025).
adenocarcinoma (continued). "Similarly, BRAF mutations are much more common in lung premalignant lesions than in adenocarcinomas, raising the possibility that BRAF mutations in lung epithelium could similarly reside on decoy adaptive peaks." (PMID 30848555, 2019). "However, more plausible explanations include de novo developments from normal lung epithelium to KRAS- or BRAF-mutated invasive adenocarcinomas as a result of KRAS or BRAF mutations and additional genomic changes, including genomic instability caused by defective DNA repair or smoking." (PMID 29690599, 2018). "A study of 102 cases of LCLC revealed that adenocarcinoma-associated mutations (EGFR, KRAS, BRAF, and ALK) occurred exclusively in the null immunophenotype or adenocarcinoma-differentiated LCLC." (PMID 40898486, 2025). "In contrast, mixed well-to-poorly differentiated adenocarcinomas were less frequent in the BRAF/NRAS group (three of six cases, 50.0%) than in the KRAS (33 of 39 cases, 84.6%) or WT (21 of 27 cases, 77.7%) groups." (PMID 41439081, 2025). "Case studies have reported benefit of BRAF/MEK inhibition in BRAF mutated colorectal NEC, and a BRAF/EGFR-inhibitor combination is approved for BRAF mutated CRC, not limited to adenocarcinomas." (PMID 38909137, 2024). "The histological subtype was largely Lieberkuhnian adenocarcinoma (95%), and KRAS, NRAS and BRAF genes were mutated in 58%, 4% and 8% of cases, respectively." (PMID 39796718, 2024). "In Villaruz’s study, 21 cases (2.2%) of 951 adenocarcinomas proved to be BRAF mutant, 81% of which were V600E." (PMID 38953007, 2024). "EGFR mutations, ALK translocations, ROS1 aberrations and BRAF mutations are now routinely evaluated in advanced non-small cell lung cancer (NSCLC), especially in adenocarcinoma." (PMID 38200537, 2024). "KRAS, BRAF, STK11/KEAP1, MUTYH/RET, and RBM10/MET-associated modules showed the opposite trend, having significantly higher frequencies of adenocarcinoma cases as genomic alterations increased (P ≤ 0.02)." (PMID 39664186, 2024). "Our finding is in huge contrast to the substantial shorter survival found when BRAF mutation is present in metastatic colorectal adenocarcinoma supporting that colorectal NEC and adenocarcinoma are separate entities." (PMID 38909137, 2024). "Most prevalent actionable mutations in adenocarcinoma include KRAS, EGFR, ALK, RET, ROS1, BRAF, HER2, MET." (PMID 37301854, 2023). "The occurrence rate of BRAF fusions is smaller than 1% in NSCLC, and all NSCLCs with BRAF fusions were adenocarcinomas or NSCLC with adenocarcinoma features." (PMID 35433454, 2022). "The first case is a 64‐year‐old woman with RAS and BRAF wild‐type adenocarcinoma of the cecum, first diagnosed in 08/2017." (PMID 34873826, 2022). "BRAF mutations have been found in 1–4% of all NSCLC (1–2% of NSCLC patients are BRAF-V600E mutations), most commonly in patients with adenocarcinomas." (PMID 36361201, 2022). "The second case represents a 73‐year‐old woman with BRAF V600E‐positive adenocarcinoma of the colon." (PMID 34873826, 2022). "Colonic adenocarcinomas that were BRAF and KRAS wild types had moderate to strong nuclear staining, and weak to negative cytoplasmic staining." (PMID 34201061, 2021). "Our results suggest that BRAF-mutant clones are enriched through EGFR-directed therapy in EGFR-mutant adenocarcinoma." (PMID 34921211, 2021). "Compared to conventional adenocarcinoma, CNEC frequently exhibited BRAF mutations (59% vs. 5%) and less frequently displayed KRAS mutations (17% vs. 43%); the large majority (93%) of CNECs showed proficient mismatch repair." (PMID 29652830, 2018).
adenocarcinoma (continued). "The 5.3% frequency of exon 14 MET mutations was derived from 150 adenocarcinomas carrying similar mean gene mutation frequencies as those previously reported in France for KRAS (23.3%), EGFR (9.3%), and BRAF (0.3%)." (PMID 28418914, 2017). "In wild type KRAS/BRAF invasive adenocarcinomas with nuclear beta-catenin, increased c-MYC expression was associated with an up-regulation of SIRT1." (PMID 23045412, 2012). "Seven of 34 serrated adenocarcinomas showed MSI-H (20.6%), and five of them (71.4%) had a concurrent BRAF mutation (P = 0.075)." (PMID 21457162, 2011). "The distribution of PTEN, PIK3CA, BRAF and K-RAS mutations and loss of PTEN expression in the 186 adenocarcinomas available from EPIC Norfolk." (PMID 21473780, 2011). "Of the four adenocarcinomas which exhibited mutations in PTEN exons 7 and 8, all also harboured BRAF mutations." (PMID 21473780, 2011). "Significant differences in gender (33.3% vs 62.3%, p=0.012), smoking history (22.2% vs 43.1%, p=0.063), and adenocarcinomas (100% vs 83.6%, p=0.028) were observed between primary BRAF/EGFR co-mutated and non-co-mutated groups." (PMID 40242250, 2025). "BRAF mutations were detected in 141 out of 5064 adenocarcinomas (ADCs) (2.78%) and 9 out of 1546 non-ADCs (0.58%)." (PMID 38394545, 2024). "While BRAF mutations are predominantly found in adenocarcinomas (>85%), there is no clear association of BRAF mutation status with other patient characteristics, such as age, ethnicity, and sex6,8,9,26." (PMID 38627602, 2024). "The most mutated immunophenotypes of adenocarcinomas were the undefined (1 KRAS; 2 PIK3CA, and 1 BRAF) and the biliopancreatic (2 KRAS and 1 BRAF), followed by the gynecological immunophenotype (1 case with concomitant KRAS and PDGFRA missense mutation and 1 with PIK3CA mutation)." (PMID 36346458, 2023). "Gene mutations could be safely demonstrated from the effusion cfDNA fraction obtained from adenocarcinoma patients, 3/36 EGFR, 9/36 KRAS and 1/36 BRAF gene variants were detected." (PMID 34257581, 2021). "This phenomenon, called oncogene-addiction, more often occurs in adenocarcinoma histology, in non-smokers (except BRAF mutations, also frequent in smoking patients), young, and female patients." (PMID 32397295, 2020). "KRAS and BRAF mutated CRCs are associated with distinct clinicopathological features according to a large cohort of CRC in Western entity, where RAS mutation is associated with male gender and classical adenocarcinoma subtype." (PMID 32582557, 2020). "All patients had BRAF V600E mutation without concomitant mutation and almost all had adenocarcinoma (95%)." (PMID 33276639, 2020). "Our data showed that ALK, ROS1, BRAF or KRAS gene alterations were significantly more frequent in adenocarcinomas with a mucus‐producing component or micropapillary component, and these two components could be a nonpredominant component in some cases." (PMID 32729257, 2020). "NRAS and BRAF mutations were only detected in 3.0 and 2.2% of adenocarcinomas, but not detected in other histological types." (PMID 30416987, 2018).